CCND2 (cyclin D2)
Diseases named in the same sentence as CCND2 in open-access papers (continued):
Sharing a sentence is not in itself a finding about the gene and the disease.
renal cell carcinoma (3 papers, 2016 to 2021). "Loss of CCD2 gene, which encodes cyclin D2, was also observed in renal cell cancer tissues and is correlated with aberrant methylation." (PMID 32893977, 2020). "To search for a mechanism underlying the consistent loss of CCND2 in renal cell cancer, we then test the methylation of CCND2 promoter as a possible cause that lead to the silence of this gene." (PMID 27583477, 2016). "In spite of this, the role of CCND2 in renal cell cancer was less thoroughly investigated." (PMID 27583477, 2016).
rhabdomyosarcoma (3 papers, 2015 to 2017). A rare aggressive malignant mesenchymal neoplasm arising from skeletal muscle. "Li L showed that transfection with miR-1 decreases the viability of rhabdomyosarcoma proliferation by targeting CCND2." (PMID 26036633, 2015). "AZD8055 and MK2206 decreased Cyclin D2, D3 and E in Rh30 cells whereas rapamycin also decreased both Cyclin D2 and D3 but not Cyclin E (Cyclin D2 and Cyclin D3 are the major G1 phase cyclins in rhabdomyosarcoma, Shen and Houghton, unpublished)." (PMID 28484242, 2017).
schizophrenia (3 papers, 2007 to 2022). A major psychotic disorder characterized by abnormalities in the perception or expression of reality. "Interestingly, two of the genes in this network have previously been associated with schizophrenia as deregulated in postmortem brains (CCND2) or positioned under a highly significant linkage peak (PTPN1)." (PMID 17849003, 2007). "We here did a comprehensive behavioural assessment of deficits across the three symptom domains of schizophrenia in the Cyclin-D2-KO mouse model of ventral hippocampal hyperactivity." (PMID 30301879, 2018). "JUN and two of the miRNA targets (CCND2 and PTPN1) in the network have previously been associated with schizophrenia." (PMID 17849003, 2007). "Therefore, we utilized the cyclin-D2 knockout mouse model that displays certain endophenotypes and behavioral deficits that are reminiscent of the schizophrenia prodrome." (PMID 36225391, 2022). "To investigate this preclinically, we deployed the cyclin-D2 knockout mouse model (CD2-KO) that shares physiological and behavioral abnormalities with the schizophrenia prodrome, including a hyperactive CA1 region, and cognitive and affective deficits." (PMID 36225391, 2022).
seminoma (3 papers, 2016 to 2025). A radiosensitive malignant germ cell tumor found in the testis (especially undescended), and extragonadal sites (anterior mediastinum and pineal gland). "The genetic aberrations causing TGCT are complex; in fact, the development of seminomas involves triploid/tetraploid chromosomes, short arm amplification of chromosome 12, inducing CCND2 gene (cyclin D2) hyper-expression and deletions of chromosomes 1, 3 or 11 short arms." (PMID 27983647, 2016). "In summary, analysis of AACR Project GENIE data sheds light on a distinct seminoma genomic profile characterized by recurrent mutations in KIT, KRAS, and MTOR, as well as focal copy number alterations in CDKN1B, KRAS, CCND2, and H3F3C." (PMID 41154418, 2025). "Among them, we found the cell cycle- and CDK4/6-associated genes CCND2 (seminomas 9.8%, non-seminomas 16.8%), CDKN1B (P27; seminomas 15.3%, non-seminomas 16.4%) and MDM2 (seminomas 4%, non-seminomas 3.6%) commonly amplified in seminomas and non-seminomas." (PMID 32418994, 2020). "In our analysis of CNAs, we found that CCND2 is commonly amplified in seminomas and non-seminomas." (PMID 32418994, 2020).
Sepsis (3 papers, 2018 to 2022). Sepsis is defined as life-threatening organ dysfunction caused by a dysregulated host response to infection. "Our results suggested the potential cascade of rno-miR-146b-5p, Klf4, and Ccnd2 in regulating the pathogenic processes underlying sepsis-induced intestinal injury." (PMID 33200654, 2020). "We found that Ccnd2 is an important factor in the regulation of cell proliferation and was significantly downregulated in the sepsis group." (PMID 33200654, 2020). "rno-miR-146b-5p may play a vital role in the development of sepsis intestinal injury through targeting Klf4 expression and affecting promoter activity of Ccnd2." (PMID 33200654, 2020). "Thus, we suspect that the upregulation of rno-miR-146b-5p in the sepsis model may inhibit the promoter activity of Ccnd2 owing to reduced Klf4 expression." (PMID 33200654, 2020). "mRNA sequencing data showed that Ccnd2, a molecule closely related to the cell cycle in the PI3K-Akt signaling pathway, was significantly downregulated in the sepsis group." (PMID 33200654, 2020). "However, there was no change in the expression of cyclin D2 in the same animals after sepsis (data not shown)." (PMID 30052667, 2018).
T-cell leukemia (3 papers, 2017 to 2023). A malignant disease of the T-lymphocytes in the bone marrow, thymus, and/or blood. "Pimozide, an inhibitor of USP1, results in the arrest of adult T-cell leukemia cells in the G1 phase, leading to the accumulation of p21 and p27 and reduction in the protein levels of cyclin D2, cyclin E, CDK2, CDK4, and CDK6." (PMID 36357365, 2022).
uveal melanoma (3 papers, 2012 to 2020). A melanoma derived from melanocytes of the uveal tract. "Yan and coworkers found similar effects in uveal melanoma cells, where they identified MITF, BCL2 and cyclin D2 as potential targets of miR-182." (PMID 24575749, 2014). "To examine other intracellular proteins affected by miR-182 in uveal melanoma cells, we next determined the expression patterns of intracellular proteins directly affected by miR-182, including BCL2, cyclin D2, and other cell cycle related proteins." (PMID 22848417, 2012).
Wilms tumor (3 papers, 2008 to 2022). An embryonal neoplasm characterized by the presence of epithelial, mesenchymal, and blastema components. "Though CNVs in genes involved with cell cycle regulation were evident, such as CDK4 and CCND2 copy number gains (three copies of each gene) compared to primary Wilms tumor samples [HT98 and HT139]." (PMID 36612255, 2022). "HOXA11-AS recruits FOXP2, positively regulates the transcription of Cyclin D2, inhibits apoptosis, and promotes cell cycle progression in nephroblastoma." (PMID 36057597, 2022).
acute lymphoblastic leukemia (2 papers, 2014 to 2018). Leukemia with an acute onset, characterized by the presence of lymphoblasts in the bone marrow and the peripheral blood. "For example, our method recognizes genes that codify for cyclin D2 (protein involved in cell cycle), neprilysin (an enzyme common in acute lymphoblastic leukemia), a protein-tyrosine phosphatase of T-cells and a protein similar to phorbolin-1 (that can be expressed in leukocytes)." (PMID 30200879, 2018).
colon adenoma (2 papers, 2005 to 2022). An adenoma that arises from the colon. "In addition, in flat and exophytic human colon adenomas, cyclin D2 was overexpressed in considerably larger proportions than cyclin D1." (PMID 16012517, 2005).
COVID-19 (2 papers, 2022 to 2024). A disease caused by infection with severe acute respiratory syndrome coronavirus 2. "Additionally, we found 44, 42, and 53 up-DEGs that were notably associated with mild, moderate, and severe COVID-19, and there were six significant common genes across three phases of COVID-19, including TCF7, GZMH, RAB5IF, CCND2, BIRC6, and NDUFAF3." (PMID 35172892, 2022).
ductal carcinoma in situ (2 papers, 2007 to 2016). "and its presence in ductal carcinoma in situ suggests that transcriptional silencing of Cyclin D2 by hypermethylation is an early event in breast tumorigenesis." (PMID 17324252, 2007).
esophageal squamous cell carcinoma (2 papers, 2013 to 2023). Esophageal squamous cell carcinoma (ESCC) is a type of esophageal carcinoma (EC) that can affect any part of the esophagus, but is usually located in the upper or middle third. "Additionally, Ding and colleagues reported that upregulation of miR-29c downregulated cyclin E and suppressed its oncogenic activity in esophageal squamous cell carcinoma, without affecting other G1 phase-related proteins level, such as cyclin D1, cyclin D2." (PMID 23383003, 2013).
Immunodeficiency (2 papers, 2007 to 2022). Failure of the immune system to protect the body adequately from infection, due to the absence or insufficiency of some component process or substance. "Thus, cyclin D2 null mice may be expected to be deficient in host defense against bacterial pathogens; indeed, cyclin D2-/- mice display specific immunodeficiency in IgG3 as well as in IgA levels." (PMID 17295909, 2007).
megalencephaly-polymicrogyria-polydactyly-hydrocephalus syndrome (2 papers, 2021 to 2023). "De novo CCND2 variants leading to stabilization of cyclin D2 are known to cause megalencephaly-polymicrogyria-polydactyly-hydrocephalus syndrome (MPPH), which is a rare megalencephaly syndrome." (PMID 37501076, 2023). "Megalencephaly-polymicrogyria-polydactyly-hydrocephalus (MPPH) syndrome is caused by mutations, in order of frequency, of either PIK3R2, AKT3, or CCND2 genes with consequent activation of the PI3K-AKT-mTOR pathway." (PMID 35096710, 2021).
mesothelioma (2 papers, 2018 to 2022). A usually malignant and aggressive neoplasm of the mesothelium which is often associated with exposure to asbestos. "Furthermore, lower expression of CDK7, AKT1, PARP1 (p < 0.1), CCND2 (cyclin D2), CDK2, CDK4, BIRC5 (survivin), PCNA and CDH2 (N-cadherin) (p < 0.005) have been shown to result in longer median survival of patients with mesothelioma." (PMID 36304150, 2022).
mucosal melanoma (2 papers, 2020 to 2025). A melanoma that arises from a mucosal site. "The driver mutations in the genes RICTOR, CDK4, PDGFRA, KIT were specific for acral melanoma, while the amplification or deletion of the genes CCND2 and CHEK2 are uniquely found in mucosal melanoma." (PMID 32825510, 2020).
ovarian tumors (2 papers, 2016 to 2019). "For example, E2 increased expression of the cyclin dependent kinase 2 (Ccnd2) gene, which is altered (via amplification or mRNA upregulation) in 12 % of ovarian tumors, and has been shown to be upregulated in some OVCAs." (PMID 26879975, 2016).
pancreatic adenocarcinoma (2 papers, 2018 to 2019). "CCND2 plays an important role in the proliferation of pancreatic islet b-cell and the mRNA expression of CCND2 is rarely detected in pancreatic adenocarcinoma cell lines." (PMID 29596435, 2018). "It has been found that CCND2 is hypermethylated in the progression of pancreatic adenocarcinoma." (PMID 29596435, 2018).
polydactyly (2 papers, 2018 to 2024). A disease characterized by the presence of polydactyly, including syndromic and non-syndromic forms. "Because of the co-occurrence of macrocephaly and polydactyly, a combination of phenotypes often observed in mTOR hyperactivation disorders, which result in CCND2 stabilization, we hypothesized that the MAXArg60Gln variant may also result in CCND2 stabilization." (PMID 38141607, 2024).
acute leukemia (1 paper, 2014). A clonal (malignant) hematopoietic disorder with an acute onset, affecting the bone marrow and the peripheral blood. "The over-expression of cyclin D2 has been observed in many tumors including acute leukemia, and may contribute to unlimited cell division, prevention of programmed death and chemoresistance." (PMID 24743557, 2014).
Alzheimer disease (1 paper, 2021). A progressive, neurodegenerative disease characterized by loss of function and death of nerve cells in several areas of the brain leading to loss of cognitive function such as memory and language. "The major novelty of this study is demonstrating that the expression of cyclin D2 (cD2) is uniformly decreased in all tested conditions related to the pathomechanism of Alzheimer’s disease (AD), including Aβ toxicity, neuroinflammation and human post-mortem brain tissue from AD patients." (PMID 34793515, 2021).
American trypanosomiasis (1 paper, 2022). A parasitic infection caused by Trypanosoma cruzi. "CircRNA_400090 could regulate the expression of FOXO1, CCND2 and SMAD2 to participate the pathways of hsa04068: FoxO signalling pathway or hsa05142: Chagas disease (American trypanosomiasis)." (PMID 35840955, 2022).
anaplastic thyroid carcinoma (1 paper, 2015). "CCND2 is underexpressed in ATC and there are no overexpressed CCNDs in anaplastic thyroid carcinoma, suggesting an abscence of progression of the cell-cycle via cyclins in ATC." (PMID 25887408, 2015).
astrocytic tumor (1 paper, 2010). A glial tumor of the brain or spinal cord showing astrocytic differentiation. "We assessed the hypermethylation status of the Cyclin D2 promoter in 8 cell lines and 44 astrocytic tumors by studying two putative CpG islands." (PMID 21059263, 2010). "However, only 4 astrocytic tumor samples (3, 13, 18 and 24) demonstrated Cyclin D2 promoter hypermethylation by both methods." (PMID 21059263, 2010).
B-cell neoplasm (1 paper, 2023). A group of heterogeneous lymphoid tumors generally expressing one or more B-cell antigens or representing malignant transformations of B-lymphocytes. "However, the expression of CCND2 or CCND3 without the presence of a detectable translocation, particularly in SOX11-negative tumours, should not be considered as evidence of MCL since B cell neoplasms express variable levels of CCND2 or CCND3 without translocations of these genes." (PMID 36454275, 2023).
brain malformations (1 paper, 2019). "A targeted next‐generation sequencing of a panel of 182 genes associated with brain malformations performed using a SureSelect custom capture (Agilent Technologies, Santa Clara, CA) revealed an heterozygous CCND2 variant NM_001759.3: c.839C>T, p.(Thr280Ile)." (PMID 31056854, 2019).
breast adenocarcinoma (1 paper, 2023). "We found no relevant expression of cyclin D2 in MDA-MB-231 Br4 cells, in line with the previous reports of lack of expression in cultured BC cells and in breast adenocarcinoma tissue." (PMID 37568789, 2023).
chondrosarcoma (1 paper, 2025). A malignant cartilaginous matrix-producing mesenchymal neoplasm arising from the bone and soft tissue. "FGF2 treatment caused an elevation in the expression of p21, leading to the formation of complexes involving cyclin D2-Cdk4-p21, cyclin D2-Cdk2-p21, and cyclin E-Cdk2-p21, and reducing the activity of cyclin-dependent kinase 2 (Cdk2) and cyclin E-dependent kinases in rat chondrosarcoma cells." (PMID 40256430, 2025).
colorectal adenocarcinoma (1 paper, 2015). The most common type of colorectal carcinoma. "Sulforaphane, a bioactive component of cruciferous vegetables, down-regulates DNMT1 and induces demethylation of the Cyclin D2 (CCND2) gene in the human colorectal adenocarcinoma Caco-2 cell line." (PMID 25875118, 2015).
colorectal tumors (1 paper, 2014). "CCND2 is a critical mediator of cell cycle control (from G1 to S phase) and is overexpressed in a substantial proportion of human colorectal tumors." (PMID 24968322, 2014).
cystitis (1 paper, 2021). Inflammation of the urinary bladder. "For this reason, the present study speculates and validates that miR-211 regulates the proliferation and invasion of glandular cystitis cells through targeted regulation of CCND2." (PMID 32820798, 2021).
emphysema (1 paper, 2011). "While CCND2 hypermethylation could be part of the unique pathophysiology of emphysema, it more likely arose because emphysema reflects severe smoking-induced lung damage." (PMID 21577262, 2011). "In weighing the relative contributions of age, sample location, and emphysema status on CCND2 hypermethylation, it is worth noting that smoking history was by far the strongest single predictor of CCND2 hypermethylation in univariate analysis (OR = 6.9, 95% CI = 1.6–29.8)." (PMID 21577262, 2011).
endothelial dysfunction (1 paper, 2023). In vascular diseases, endothelial dysfunction is a systemic pathological state of the endothelium (the inner lining of blood vessels) and can be broadly defined as an imbalance between vasodilating and vasoconstricting substances produced by (or acting on) the endothelium. "Furthermore, it has been reported that CCND2 is one of the most important biomarkers of endothelial dysfunction." (PMID 36968605, 2023).
extragonadal germ cell tumor (1 paper, 2024). A germ cell tumor arising in an anatomic site other than the testis or ovary (e.g., central nervous system, lung, mediastinum, and retroperitoneum). "Mutations in the CCND2 and RB1 genes have been associated with the development of extragonadal germ cell tumors (EGCTs) found in the mediastinum." (PMID 39045558, 2024).
HIV-1 infection (1 paper, 2016). The type species of lentivirus and the etiologic agent of acquired immunodeficiency syndrome (AIDS). "We have identified cyclin D2 as the key step controlling susceptibility to HIV-1 infection by modulation of the signaling pathway leading to SAMHD1 phosphorylation." (PMID 27541004, 2016). "Stimulation of monocytes with GM-CSF induces a non-proliferating macrophage population highly restrictive to HIV-1 infection, characterized by the upregulation of the G1/S-specific cyclin D2, known to control early steps of cell cycle progression." (PMID 27541004, 2016). "Accordingly, knockdown of cyclin D2 and cyclin D3 resulted in opposite effects depending on the macrophage type, in terms of susceptibility to HIV-1 infection: cyclin D2 restricts infection in non-cycling GM-CSF macrophages and cyclin D3 enables infection in proliferating M-CSF macrophages." (PMID 27541004, 2016).
infarction (1 paper, 2025). A localised pathological necrosis of tissue resulting from obstruction of the blood supply usually by a thrombus, an embolus, or vascular torsion. "Notably, utilizing a cardiomyocyte-specific mRNA translation system (SMRTs) to overexpress Cyclin D2 (CCND2) resulted in enhanced CM proliferation and myocardial repair post-infarction." (PMID 41015973, 2025).
insulinoma (1 paper, 2018). "As already mentioned, it was also shown that ANP can stimulate the proliferation of cultured rat pancreatic islets β-cells and insulinoma cells (INS-1E) via GC-A/cGMP-dependent activation of phosphatidylinositol 3′-kinase and Akt/Foxo1a/cyclin-D2 signaling." (PMID 30016962, 2018).
invasive ductal carcinoma (1 paper, 2007). "Of those previously affected by contralateral invasive ductal carcinoma, two were found have hypermethylation of HIN-1 and one also had hypermethylation of Cyclin D2." (PMID 17324252, 2007).
Iron deficiency (1 paper, 2025). "Iron deficiency arrested mouse estrous cycles at diestrus, blocked secondary follicular development and ovulation due to reduced ovarian ATP levels, downregulation of follicular development markers (FSHR, CYP19A1, CCND2), and decreased estradiol—17β (E2) compared to controls." (PMID 41169787, 2025).
ischemic cardiomyopathy (1 paper, 2026). Ischemic cardiomyopathy is a cardiomyopathy in which a weakness in the muscle of the heart due to inadequate oxygen delivery to the myocardium with coronary artery disease being the most common cause. "The hub genes, including STAT3, MDM2, LRP1, IRS2, PRKCD, CCND2, and CISH, were validated to be highly expressed in adipocytes in ischemic cardiomyopathy patients with end-stage heart failure." (PMID 41869532, 2026).